THOC3 (THO complex subunit 3)
Description:
Component of the THO subcomplex of the TREX complex which is thought to couple mRNA transcription, processing and nuclear export, and which specifically associates with spliced mRNA and not with unspliced pre-mRNA. Required for efficient export of polyadenylated RNA and spliced mRNA. The THOC1-THOC2-THOC3 core complex alone is sufficient to bind export factor NXF1-NXT1 and promote ATPase activity of DDX39B. TREX is recruited to spliced mRNAs by a transcription-independent mechanism, binds to mRNA upstream of the exon-junction complex (EJC) and is recruited in a splicing- and cap-dependent manner to a region near the 5' end of the mRNA where it functions in mRNA export to the cytoplasm via the TAP/NXF1 pathway. (Microbial infection) The TREX complex is essential for the export of Kaposi's sarcoma-associated herpesvirus (KSHV) intronless mRNAs and infectious virus production.
Synonyms: Tho3; TEX1; MGC5469; hTREX45
Tractability: PROTAC: ubiquitination databases record sites on it; its protein half-life has been measured.
Gene: Protein-coding gene on chromosome 5 (175,916,677 to 176,034,680, reverse strand). Ensembl gene ENSG00000051596.
Subcellular location: Nucleus; Nucleus speckle
Subcellular location (Human Protein Atlas): Nucleoplasm; Vesicles
Pathways (Reactome):
Metabolism of RNA: Transport of Mature mRNA derived from an Intron-Containing Transcript; mRNA 3'-end processing
Gene Ontology:
Biological process: mRNA export from nucleus
Cellular component: chromosome, telomeric region; nucleoplasm; THO complex part of transcription export complex; transcription export complex; nuclear speck; nucleus
Genetic constraint (gnomAD): Loss-of-function variants: 3 observed, 7.73 expected, observed/expected ratio (o/e) 0.39, 90% interval 0.18 to 1. That is too few expected variants to judge how well the gene tolerates losing a copy. Missense variants: 51 observed, 131.22 expected, observed/expected ratio (o/e) 0.39, 90% interval 0.31 to 0.49. Synonymous variants: 22 observed, 42.97 expected, observed/expected ratio (o/e) 0.51, 90% interval 0.37 to 0.73.
Homologues: Orthologues: chimpanzee THOC3 (100% identical), macaque THOC3 (99% identical), mouse Thoc3 (99% identical), pig THOC3 (99% identical), rat Thoc3 (99% identical), rabbit THOC3 (99% identical), dog THOC3 (90% identical), guinea pig THOC3 (83% identical), zebrafish thoc3 (83% identical), tropical clawed frog thoc3 (83% identical), Drosophila melanogaster tex (56% identical).
Diseases named in the same sentence as THOC3 in open-access papers:
THOC3 is named in the same sentence as 14 diseases in open-access papers, as found by Europe PMC text mining. Sharing a sentence is not in itself a finding about the gene and the disease. The quoted sentences say what the papers report.
glioma (2 papers, 2021). A benign or malignant brain and spinal cord tumor that arises from glial cells (astrocytes, oligodendrocytes, ependymal cells). "THOC3 was involved in the THO subcomplex, which was necessary for coupled mRNA transcriptional extension and nuclear export, its expression was significantly elevated in glioma cells." (PMID 34482648, 2021). "THOC3 is involved in the THO subcomplex and is necessary for coupled mRNA transcriptional extension and nuclear export, and its expression is significantly elevated in glioma cells." (PMID 35126467, 2021).
breast carcinoma (1 paper, 2011). "We evaluated the expression of the components of the human THO complex, THOC1, THOC2, THOC3, THOC5, THOC6 and THOC7, as well as the expression levels of UAP56 and ALY in breast cancer cell lines." (PMID 21329510, 2011).
lung squamous cell carcinoma (1 paper, 2023). "In this study, we identified that THOC3 was highly expressed in lung squamous cell carcinoma (LUSC) and negatively associated with prognosis." (PMID 37500615, 2023).
cancer (4 papers, 2023 to 2024). A tumor composed of atypical neoplastic, often pleomorphic cells that invade other tissues. "Pan-cancer analysis showed that THOC3 is pervasively overexpressed in multiple malignancies compared with normal tissues." (PMID 37500615, 2023).
tumor (3 papers, 2020 to 2023). "LUSC cells were injected into BALB/c-nude mice, and THOC3 knockdown was found to inhibit the increase in tumor volume and weight, as well as suppress lung metastasis." (PMID 37500615, 2023). "Results of rescue experiments indicated that PFKFB4, as the downstream of THOC3, could mediate tumor-promoting effects in LUSC cells." (PMID 37500615, 2023). "In mouse subcutaneous tumor models, knockdown of THOC3 inhibited the proliferation of tumor." (PMID 37500615, 2023). "In the subnetwork related to tumor progression, the hubs from the blue module are the most connected, such as the genes Cmas, Kmt2a, Golt1b, Cdc34, Manf, Sco1, and Thoc3, followed by hubs from the light cyan (Extl2, Commd3, Wdr41, Keap1, Osbpl9) and pink modules." (PMID 32831131, 2020). "Furthermore, we demonstrated the tumor-promoting role of THOC3 in vivo." (PMID 37500615, 2023). "In subcutaneous tumor models, THOC3 knockdown inhibited the expression of PFKFB4, and THOC3 overexpression increased its level." (PMID 37500615, 2023). "However, the role of THOC3 in tumor has not been systematically studied." (PMID 37500615, 2023).
THOC3 also shares sentences with these, for which no sentence is quoted: infection (3 papers); malaria (3); co-infection (1); lung adenocarcinoma (1); lung carcinoma (1); neurodegenerative disease (1); neurologic disorder (1); pancreatic tumors (1); parasitemia (1).